IL6 (interleukin 6)
Diseases named in the same sentence as IL6 in open-access papers (continued):
Sharing a sentence is not in itself a finding about the gene and the disease.
thrombotic disease (10 papers, 2021 to 2025). The formation of a blood clot in the lumen of a vessel or heart chamber; causes include coagulation disorders and vascular endothelial injury. "It is well known that IL-6 induces platelet activation, causing endothelial damage and thrombotic disorders with increased D-dimer production." (PMID 40241896, 2025). "Logistic regression analysis identified IL-6 and integrin β1–3 levels as independent risk factors for thrombotic disease." (PMID 37998519, 2023). "Circulating IL-6 has been known to regulate fibrinogen—an acute-phase protein which is recognized as an important risk factor for atherosclerotic and thrombotic diseases." (PMID 34595552, 2021). "Inflammatory markers, such as C-reactive protein (CRP), interleukin-6 (IL-6), and fibrinogen, have been widely studied in various diseases, including cancer and thrombotic disorders." (PMID 41169874, 2025). "Considering that TNFα was identified as an upstream regulator in the HCM LA and IL6 was found to be relevant in HCM (particularly in cats with atrial thrombus), an involvement of T cells in atrial changes in HCM seems likely." (PMID 36928240, 2023). "Furthermore, it would be interesting to identify how far IL-6 signaling is active in DVT patients and understand the influence of pleiotropic IL-6 on the potential outcome of thrombotic disease." (PMID 35625609, 2022).
thymic atrophy (10 papers, 2004 to 2025). "Elevated plasma cortisol levels were detected in all CHD patients, while high NT-proBNP and IL-6 levels were associated with thymic atrophy." (PMID 38393459, 2024). "Interestingly, IL-6 has also been involved in some cases of thymus atrophy, as thymic depletion due to age or fetal thymic atrophy caused by LPS treatment, indicating a possible link between IL-6 and thymic alterations." (PMID 28147332, 2017). "Compared with their less active counterparts, the cyclists had significantly higher serum levels of the thymoprotective cytokine IL‐7 and lower IL‐6, which promotes thymic atrophy." (PMID 29517845, 2018). "The molecular basis of thymic involution in our patient groups was unclear, we hypothesise that an elevated level of IL-6 is a contributing factor as inflammation drives thymic atrophy." (PMID 40908179, 2025). "We observed that TPSs significantly increased the body weight and alleviated CTX-induced thymus atrophy in the immunosuppressed mice; they also increased the plasma levels of immunoglobulins A and M, interleukin (IL) 1β, IL-6, inducible nitric oxide synthase, and tumor necrosis factor α." (PMID 39335922, 2024). "Finally, similar defects in DN differentiation may contribute to thymic atrophy in other infections where IL-6 is elevated." (PMID 28147332, 2017). "In Harbor porpoises, neither IL-6 nor TNF-α were associated with severely diseased individuals, those with splenic depletion, or the degree of thymic atrophy." (PMID 36230446, 2022). "We observed increased expression of Il6 in the thymus of infected mice, which is in accordance with a study showing that over-expression of IL-6 inhibits the differentiation of double negative (DN) thymocytes in a model of T. cruzi infection-induced thymic atrophy." (PMID 34987496, 2021).
toxoplasmosis (10 papers, 2008 to 2024). A parasitic disease contracted by the ingestion or fetal transmission of toxoplasma gondii. "The relationship between IL‐6 polymorphism and the risk of toxoplasmosis in HIV‐positive patients has notfound, however, been the subject of similar studies." (PMID 38270309, 2024). "GC heterozygotes at the IL6 −174 G>C SNP were significantly associated with toxoplasmosis and increased the risk of T. gondii infection [odds ratio (OR) 4.24, 95 % confidence interval (CI) 1.24–14.50 in the codominant model, p ≤ 0.050]." (PMID 26385345, 2015). "Although previous studies have discussed the association between IL‐17 and IL‐6 polymorphisms and ocular and congenital toxoplasmosis, there is no study evaluating these polymorphisms in HIV‐positive patients with toxoplasmosis." (PMID 38270309, 2024). "A study has shown that giving honey to toxoplasmosis-infected mice decreased TNF-α mRNA expression but maintained IL-6 mRNA expression." (PMID 36358526, 2022). "Toxoplasmosis has a strong effect on the concentration of various cytokines, especially interleukin (IL)-10, IL-5, IL-6, and transforming growth factor beta (TGF-β)." (PMID 34583758, 2021). "High IL-6 levels induce an increase in intraocular inflammation, as seen in idiopathic uveitis and ocular infection such as toxoplasmosis gondii." (PMID 29944680, 2018). "Previous studies in bovine neosporosis and murine toxoplasmosis also revealed an upregulation of IL-6 in placentas at mid-gestation." (PMID 26739099, 2016). "Further, an association between increased peripheral levels of pro-inflammatory cytokines, such as IL-6 and TNF, and elevated cerebrospinal fluid levels of IL-6, in response to toxoplasmosis, has recently been associated with self-directed violence and suicide attempts." (PMID 28075410, 2017). "The linear regression model was used to analysis of interleukin (IL)‐17A, IL‐17F, and IL‐6 single‐nucleotide polymorphism genotypes in HIV patients with and without toxoplasmosis." (PMID 38270309, 2024). "Allele frequencies of IL‐17A, IL‐17F, and IL‐6 polymorphisms in HIV patient with and without toxoplasmosis." (PMID 38270309, 2024). "Susceptibility to toxoplasmosis was not due to defective expression of IFN-γ, TNF-α, NOS2 or IL-6 in the retina and brain, differences in IL-10 expression in these organs or to impaired induction of T. gondii-reactive T cells." (PMID 23990781, 2013). "The presence of the same pathology in mice without NRAMP, IL-4, IL-6, or IL-13, each important in immunity to toxoplasmosis, indicates that none of these genes or cytokines are necessary or sufficient to cause this histopathology." (PMID 18947414, 2008). "In addition to IFN-γ, TNF-α, cerebral and ocular mRNA levels of IL-6, NOS2 and IL-10 are increased in the brain and eye of mice infected with T. gondii, and these molecules promote protection against toxoplasmosis while in the case of IL-10, this cytokine modulates susceptibility to disease –." (PMID 23990781, 2013). "Genotype analysis of IL‐17A, IL‐17F, and IL‐6 serum level in HIV patient with and without toxoplasmosis." (PMID 38270309, 2024). "Regression analysis of IL‐17A, IL‐17F, and IL‐6 SNP genotypes in HIV patients with and without toxoplasmosis." (PMID 38270309, 2024).
urolithiasis (10 papers, 2014 to 2024). Stone(s) within the urinary tract. "Intriguingly, we noticed that a higher genetically predicted IL6 level was significantly associated with an increased risk of urolithiasis (P = 0.0408157), supported by the MR-egger method." (PMID 37624788, 2023). "Unfortunately, none of the studied haplotypes were significantly associated with urolithiasis in the case of IL-6 and NOS2 genes." (PMID 37878647, 2023). "Previous studies showed that renal cell injury and inflammation relating to the development of renal stones were associated with an increase in IL-6 in the urine of patients with urolithiasis." (PMID 34440695, 2021). "Salivary levels of IL-6 and IL-17 were significantly higher in patients with calculus associated CP compared to healthy subjects." (PMID 29670909, 2018). "The current study was designed to determine level of IL-6 and IL-17 in the saliva of patients with calculus associated CP." (PMID 29670909, 2018). "Moreover, we verified the association of urolithiasis development and mRNA expression of IL-6, IL-8, SOD2, and NOS2 in peripheral blood mononuclear cells (PBMCs)." (PMID 37878647, 2023). "Thus, our presented study contained the evaluation of IL-6 and IL-8 polymorphism impact on urolithiasis occurrence." (PMID 37878647, 2023). "Interestingly, we were the first who analysed the impact of IL-6 and IL-8 SNPs on the risk of urolithiasis occurrence." (PMID 37878647, 2023). "It was reported that patients of urolithiasis were associated with elevated level of IL-6." (PMID 28116040, 2017). "The results of IL-6 in the group of patients with urolithiasis were significantly higher than in the control group." (PMID 36830821, 2023). "Our additional analysis showed a significant effect of gender and BMI on the differences in the expression level of IL-8 (p < 0.05) and IL-6 (p < 0.05), respectively, between the control group and urolithiasis." (PMID 37878647, 2023). "On the other hand, the earlier study confirmed that the kidney tissue of patients with urolithiasis exhibited a higher mRNA expression of IL-6 than healthy volunteers." (PMID 37878647, 2023). "However, the IL-6 levels on the first post-intervention day increased compared to the pre-intervention measurements in patients with urolithiasis treated with URS treatment." (PMID 38327930, 2024). "Based on our research findings, it is evident that the concentration of IL-6 significantly increased in patients with urolithiasis treated with URS on the first postoperative day, whereas there was no significant change in IL-6 levels in patients treated with ESWL." (PMID 38327930, 2024). "IL-6 secretion in urolithiasis can occur through two different mechanisms." (PMID 38327930, 2024). "In conclusion, our results suggest that polymorphic variants and changes in mRNA expression of IL-6, IL8, SOD2, and NOS2 may be involved in the pathophysiology of urolithiasis." (PMID 37878647, 2023). "Moreover, our study confirmed that patients with urolithiasis were characterised by decreased IL-6, IL-8, and SOD2 mRNA expression levels compared to the controls." (PMID 37878647, 2023). "In addition, another study affirmed that urolithiasis patients were characterised by elevated IL-6 and IL-8 levels in the urine compared with controls." (PMID 37878647, 2023). "However, there was no causal association between other common risk factors (PTH, CRP, IL6, IL18, IL27, IL8, IL16, IL1Ra, coffee consumption, age of smoking initiation, smoking initiation, and cigarettes smoked per day) and urolithiasis in the meta-analysis." (PMID 37624788, 2023). "Moreover, in our study, we showed that patients with urolithiasis were characterised by reduced IL-6 and IL-8 expression in PBMCs." (PMID 37878647, 2023). "In this case, there are two different mechanisms for IL-6 secretion in urolithiasis." (PMID 27438912, 2014).
urolithiasis (continued). "Additionally, IL-6 levels offer valuable insights for research, enabling investigations into correlations with patient outcomes, complications, and treatment efficacy in urinary stone management involving ESWL and URS." (PMID 38327930, 2024). "As one of the proinflammatory cytokines, IL-6 may be involved in pathogenesis of urolithiasis." (PMID 28116040, 2017). "Analysis of mRNA expression of IL-6 (p < 0.05), IL-8 (p < 0.001), and SOD2 (p < 0.01) showed a significant decrease in mRNA level in patients with urolithiasis compared to the controls." (PMID 37878647, 2023). "In this concept we tried to identify “markers” of inflammation (serum IL-6 and TNF-α) that would potentially aid in identifying those patients with urinary stones that are more prone to the postoperative development of infectious complications." (PMID 27469190, 2014). "Moreover, we have performed an additional analysis of IL-6, IL-8, SOD2, and NOS2 expression in the genotype groups of controls and patients with urolithiasis." (PMID 37878647, 2023). "We also showed that, unlike leptin, ghrelin correlates with other outcomes such as IL-6, TNF-α, and UA only in the group of people with urolithiasis which may be helpful in further research on appetite hormones in patients with this condition." (PMID 36830821, 2023). "Additionally, Hasna and colleagues (2015) found that diabetic patients with urolithiasis were characterised by higher CRP and IL-6 levels than diabetes mellitus cases without urolithiasis." (PMID 34440695, 2021).
vaginal infection (10 papers, 2011 to 2025). "Vaginal infections are often accompanied by desquamation and keratinization, driven by an IL‐6‐mediated pro‐inflammatory response." (PMID 41268882, 2025). "In this study, the inflammatory profile was assessed by measuring levels of four pro-inflammatory cytokines, IL-6, IL-1β, TNF-α, and IL-8, known to be associated with inflammatory processes linked to vaginal infections." (PMID 38337685, 2024). "This modulation is associated with a significant reduction in the secretion of three key pro-inflammatory cytokines, IL-6, IL-1α, and IL-1β, which are typically upregulated during C. albicans vaginal infection and contribute to the inflammatory milieu." (PMID 39770658, 2024). "Enhanced pro-inflammatory responses to vaginal infection or periodontal disease are suggested to be detrimental to pregnancy and elevated levels of IL-6 have been found to be a predictor of pre-term labor." (PMID 26106385, 2015). "Women with low capacity to respond to vaginal infection through the production of pro-inflammatory cytokines, interleukin (IL)-1β, IL-6, and IL-8 might have a more permissive environment for pathogens to flourish and be at risk of ascending uterine infection and chorioamnionitis." (PMID 26106385, 2015). "Group M presented that expression levels of IFN-γ, IL-17, IL-6, TGF-β, IL-4, and IL-10 were significantly elevated in vaginal secretions after CA vaginal infection." (PMID 35958550, 2022). "The second of these was assessed with a multi-analyte flow assay kit to determine the levels of IL-6, TNF-α, IL-1β, IL-10, IL-1α, IL-17a, MCP-1, and IFN-γ in the supernatant of cervical tissue homogenate of GrpE-immunized mice and control groups after vaginal infection." (PMID 32849509, 2020).
acute monocytic leukemia (9 papers, 2012 to 2025). Acute monoblastic leukemia (AML-M5), is one of the most common subtypes of acute myeloid leukemia (AML) that is either comprised of more than 80% of monoblasts (AML-M5a) or 30-80% monoblasts with (pro)monocytic differentiation (AML-M5b). "Third, the production of CSF3, IL-1β, and IL-6 was evaluated in EV71-infected human acute monocytic leukemia cells (THP-1), differentiated macrophages derived from THP-1 cells (macrophages), and human PBMCs cells." (PMID 28854257, 2017). "For the analysis of IL-6 removal by the engineered bacteria, we used the immunostimulated THP-1 human acute monocytic leukemia cell line and the U937 histiocytic lymphoma cell line." (PMID 35155394, 2022). "According to pre-clinical research, after silencing PCSK9 expression with siRNA, significant reduced IL-1α, IL-6, and TNF-α expression, as well as downregulated activation of the NF-κB pathway, were observed in human THP-1 (an acute monocytic leukemia cell line) cells." (PMID 40872487, 2025). "To assess whether apoC-I modulates innate immune responses by human cells, we assessed the effect of apoC-I on IL-6 and TNF-α expression by the human acute monocytic leukemia cell line THP-1." (PMID 22883744, 2012).
alcoholic fatty liver disease (9 papers, 2015 to 2025). Lipid infiltration of the hepatic parenchymal cells that is due to alcohol abuse. "HCCs that are associated with ASH (alcoholic steatohepatitis) or NASH (non-alcoholic steatohepatitis) have a similar molecular key: the IL-6/JAK/STAT signaling pathway activated by the interleukin-6 family of cytokines." (PMID 37892997, 2023). "Moreover, berberine diminished inflammation and lowered the levels of TNF-α, IL-6, and IL-1β in rats with non-alcoholic fatty liver disease by regulating the TLR4/MyD88/NF-κB signaling pathway." (PMID 38790653, 2024). "The multitargeted effects of T4OL—simultaneously reducing inflammation (NF-κB1/IL-6), hypoxia (HIF-1α), and fibrosis (TGF-β1/MMP1)—make it a promising candidate for ALD treatment, particularly in alcoholic-steatohepatitis and early fibrosis stages." (PMID 40572736, 2025).
bronchitis (9 papers, 2013 to 2025). An acute or chronic inflammatory process affecting the bronchi. "These factors induce the release of pro-inflammatory cytokines, such as interleukin-6 (IL-6) and tumor necrosis factor-alpha (TNF-α), amplifying airway inflammation and increasing the likelihood of bronchospasm, laryngospasm, and other RAEs." (PMID 41465940, 2025). "IL-6 and sTREM-1 were significantly higher in patients with bacterial CAP compared to those with CAP of unknown origin and bronchitis." (PMID 34991507, 2022).
calcification (9 papers, 2016 to 2023). Process by which organic tissue becomes hardened by the physiologic deposit of calcium salts. "IL-6 is involved in the fibrous plaque stage of the atherosclerotic process, and high levels of IL-6 are associated with valvular calcifications." (PMID 37893519, 2023). "Pro inflammatory cytokines are elevated, with C-reactive protein (CRP) associated with coronary calcification in children, and interleukin-6 (IL-6) and CRP associated with CV mortality in adults." (PMID 36114889, 2023). "Because calcification is a common feature of the CaCl2-induced AAA model and human AAA, and IL-6 may be causally related to vascular calcification, we also evaluated the effect of MR16-1 on the extent of aortic wall calcification." (PMID 28982132, 2017). "The inflammatory marker IL-6 delivers cut-off values for the cardiovascular and operative risk profile by significant correlation with IDDM, AHT, and severe coronary calcification whereas leptin and BMI are predictive for DSWI." (PMID 32685095, 2020).
cervical tumor (9 papers, 2014 to 2025). "Additionally, IL-6 is one of the main cytokines expressed by HPV16-associated cervical tumors." (PMID 36010260, 2022). "The cervical tumor microenvironment is rich in pro-inflammatory cytokines such as interleukin-6 (IL-6), tumor necrosis factor-alpha (TNF-α), and interferon-gamma (IFN-γ), which interfere with iron metabolism and erythropoiesis." (PMID 40901092, 2025). "Here, we report the case of a patient with an advanced squamous cervical cancer associated with PLR and that was chemotherapy resistant who underwent palliative cytoreductive surgery; the patient’s cervical tumor sample showed positive staining for G-CSF and IL-6, thus indicating a CST." (PMID 36010260, 2022). "Furthermore, HPV-positive cervical tumor cells produce high levels of interleukin 6 (IL-6) for autocrine signaling and to increase STAT3 activation." (PMID 35163748, 2022). "Indeed, IL-6 has been shown to stimulate cervical tumor growth through vascular endothelial growth factor (VEGF)-dependent angiogenesis." (PMID 34246302, 2021). "The exact role of IL6 in CIN progression is still unclear; besides its increased expression reported by someone during cervical tumor development, there is the important role exerted as the master switch of acute inflammation." (PMID 30622662, 2018).